SPIB (Spi-B transcription factor)
Diseases named in the same sentence as SPIB in open-access papers (continued):
Sharing a sentence is not in itself a finding about the gene and the disease.
myocardial infarction (1 paper, 2019). Gross necrosis of the myocardium, as a result of interruption of the blood supply to the area, as in coronary thrombosis. "Intriguingly, we also found that rs909253, which is predicted to alter the binding of SPIB, is associated with increased risk for myocardial infarction, non-Hodgkin lymphoma, and psoriatic arthritis, suggesting that the onset of these complex diseases may be due in part to LTα expression levels." (PMID 31791241, 2019).
Non-Seminomatous Germ Cell Tumors (1 paper, 2022). "In addition, SPIB exhibited the highest mutation frequency in ESCA, UCEC, SKCM, Non-Seminomatous Germ Cell Tumors, COAD, HNSC, Non-Small Cell Lung Cancer, and SARC." (PMID 35969172, 2022).
Primary immunodeficiency (1 paper, 2022). "KEGG analysis showed that genes associated with SPIB expression were enriched in Cytokine-cytokine receptor interaction, NF-kappa B signaling pathway, Primary immunodeficiency, Human T-cell leukemia virus 1 infection, and B cell receptor signaling pathway." (PMID 35969172, 2022).
Sepsis (1 paper, 2022). Sepsis is defined as life-threatening organ dysfunction caused by a dysregulated host response to infection. "Sepsis-linked decrease transcription of the classical HLA gene such as HLA-DPB1 and its interplay with miR-let-7b-5p and transcription factor SPIB was observed." (PMID 35831411, 2022). "Our finding identified miR-let-7b-5p in FFL modulation, which associates SPIB and HLA-DPB1 in sepsis." (PMID 35831411, 2022).
T-cell lymphomas (1 paper, 2015). "However, the specificity of this marker is not ideal, as some proportions of the B cell and T-cell lymphomas can also be positive for SPIB." (PMID 27340692, 2015).
Waldenstrom macroglobulinaemia (1 paper, 2022). "PRDM1 is also downregulated in patients with Waldenstrom macroglobulinaemia, which is linked to elevated expression of the negative regulator SPIB." (PMID 35831623, 2022). "Our results revealed that Ezh2 inhibition increases PRDM1 and downregulates SPIB, suggesting that further investigation of Ezh2 inhibitors in the context of ABC DLBCL and Waldenstrom macroglobulinaemia could be informative." (PMID 35831623, 2022).
tumor (26 papers, 2014 to 2026). "SPIB has been shown to promote tumor aerobic glycolysis and participate in the recruitment of tumor-associated macrophages (TAMs), which promotes cancer progression." (PMID 37006438, 2023). "We found that SPIB was significantly associated with tumor immune infiltration and immune checkpoint genes in more than 35 tumors by TIMER database analysis." (PMID 35969172, 2022). "We investigated the relationship of SPIB in pan-cancer with prognosis, immune cell infiltration, tumor mutational load, and microsatellite instability and comprehensively assessed its potential as a prognostic biomarker from multiple perspectives." (PMID 35969172, 2022). "We obtained six types of immune cell infiltration scores for 9,406 tumor samples from 38 cancer types and found that high SPIB expression was significantly associated with immune infiltration in 35 tumors." (PMID 35969172, 2022). "Besides, in vivo experiments further demonstrated that UBD overexpression counteracted the suppression of tumor growth caused by SPIB knockdown." (PMID 41583390, 2026). "In addition, SPIB was negatively correlated with Tumor mutational burden (TMB) and Microsatellite instability (MSI) in most tumors." (PMID 35969172, 2022). "In addition, SPIB has been associated with tumor suppression via NF-kappa B signaling pathway, consistent with our study findings." (PMID 35969172, 2022). "To clarify whether SPIB is associated with cancer, we analyzed the mRNA expression of SPIB in normal and tumor tissues using TCGA and GTEx databases." (PMID 35969172, 2022). "NDRG1 contributes to tumor aggressiveness by cell proliferation and lipid metabolism regulation, whereas GAPVD1, INPP5A, TCN1, SAV1, RBBP8, SPIB, and UBE2A also exhibit oncogenic or tumor-suppressive properties associated with prognosis." (PMID 41511940, 2026). "SPIB also displays tumour suppressive activity which is facilitated by the activation of NFκβ and JNK signalling." (PMID 39325241, 2025). "We discovered five tumor antigens (P2RY6, PLA2G2D, RBM47, SEL1L3, and SPIB) that are significantly increased and mutated, which correlate with the survival of patients and the presence of immune cells that present these antigens." (PMID 40066453, 2025). "In clinical tumor tissues, protein expression of SPIB, PLK1, and CD24 was up-regulated, while protein expression of NTRK3 and EDA2R was down-regulated." (PMID 39596658, 2024). "Given the accurate identification of TR activities specific to tumor B-cells, including SPIB, using SCRIPro, we conducted a systematic analysis to identify tumor-specific GRNs that potentially drive malignancy." (PMID 39024032, 2024). "SPIB is a member of the E-twenty-six transcription factor family, which can suppress gene activation and functions as a tumor suppressor gene in cancer." (PMID 39153969, 2024). "It was found that ATT6, ERG and PLAGL1 were more expressed in high PLP2+ Tumor EPCs score group, while SPIB was more expressed in low PLP2+ Tumor EPCs score group (P < 0.001)." (PMID 38482016, 2024). "SPIB belongs to the Ets family of transcription factors which is known to be involved in tumor progression." (PMID 39654143, 2024). "Through the activation of the NFkB and JNK signaling pathways via MAP4K1 in cancer cells, SPIB functions as a tumor suppressor." (PMID 37684436, 2023). "We further confirmed that the expression level of SPIB was significantly higher in tumor tissues than in adjacent normal tissues." (PMID 37006438, 2023). "In conclusion, our comprehensive pan-cancer analysis of SPIB reveals its important role in tumor immunity, suggesting it has huge prospects for clinical application in cancer therapy." (PMID 35969172, 2022). "Our comprehensive analysis revealed that SPIB has prognostic value in various cancers and plays an important role in tumor immunity by affecting tumor-infiltrating immune cells, TMB and MSI." (PMID 35969172, 2022).
tumor (continued). "An increasing body of evidence from recently published studies suggests that SPIB plays an important role in tumor development." (PMID 35969172, 2022). "To further assess the role of SPIB in the tumor immune microenvironment, we analyzed the relationship between SPIB expression and immune infiltration score in tumors using ESTIMATE." (PMID 35969172, 2022). "Meanwhile, the roles of SPI1 and SPIB in glucose metabolism reprogramming or reciprocal interplay of malignant tumour cells with microenvironment still remains elusive." (PMID 34841706, 2021). "Our results reveal that SPI1 and SPIB exert tumour‐promoting functions driving glycolytic process and progression of cancer." (PMID 34841706, 2021). "We conclude that separating the ABC-DLBCL subset according to relative expression of the two IRF4 cofactors SPIB and BATF identifies subgroups differentially linked to previously defined features of DLBCL tumour biology." (PMID 24875472, 2014). "Similarly, tumor sphere formation assays indicated that UBD overexpression restored the reduction in tumor sphere size and number induced by SPIB knockdown." (PMID 41583390, 2026). "Tumor size reduction induced by SPIB knockdown was effectively reversed by UBD overexpression." (PMID 41583390, 2026). "SPIB knockdown reduced tumor sphere size and number, indicating impaired self-renewal." (PMID 41583390, 2026). "Furthermore, analysis of the GSE4552 dataset demonstrated that UBD and SPIB are both highly expressed in TNBC, with a statistically significant positive association between their expression levels in tumor tissues." (PMID 41583390, 2026). "In addition, we also analyzed the survival of genes which constituted PLP2+ Tumor EPCs score, and the results showed that only four of them (SPIB, ATF6, PLAGL1, ERG) were statistically significant (P<0.05)." (PMID 38482016, 2024). "The first highest order miR-200 family-associated subnetwork motif comprised miR-200a-3p, CX3CR1 and SPIB. miR-200 family has been reported to function as an oncogene or tumor-suppressor in several carcinogenesis, but its crucial biological importance and functions in NSCLC are subtle." (PMID 37770496, 2023). "In addition, SPIB staining was weak in normal lung tissue, while tumor tissue exhibited moderate staining." (PMID 35969172, 2022). "Through physical interaction with co‐factor SPIB, SPI1 exerted tumour‐promoting functions in glycolytic process and progression of cancer, shedding light on the SPIB/SPI1‐mediated positive interplay loop of cancer cells and neutrophils as a therapeutic target against cancers." (PMID 34841706, 2021). "Considering the similarity between regeneration and tumor, we inferred that SPIB may play a vital role in liver regeneration." (PMID 28752099, 2017). "We reasoned, therefore, that the relative expression of BATF and SPIB might contribute to heterogeneity of tumour biology among ABC-DLBCL." (PMID 24875472, 2014). "high PLP2+ Tumor EPCs score group highly expressed ATF6, ELF1, ERG and PLAGL1 genes, while low PLP2+ Tumor EPCs score group highly expressed ATF5, TBX21, SPIB, LHX2 and JUND genes." (PMID 38482016, 2024). "The mRNA expression of SPIB, PLK1, and CD24 is upregulated in clinical tumor tissues, whereas NTRK3 and EDA2R mRNA expression is downregulated." (PMID 39596658, 2024). "The proteins PLK1, SPIB, and CD24 show darker staining in tumor tissues, while NTRK3 and EDA2R exhibit lighter staining in tumor tissues." (PMID 39596658, 2024). "We found that the expressions of CCL1, FABP7, S100B, CTSW, and SEZ6 significantly decreased in the tumor tissue, the expression of CPLX2 and SPIB increased obviously in BC." (PMID 36581948, 2022). "This expression pattern indicated distinct roles of SPIB in CRC epithelial cells and tumor microenvironment." (PMID 34094897, 2021). "The Spi-B transcription factor protein is a member of the ETS transcription factor family, which inhibits neoangiogenesis, tumor progression, and metastasis." (PMID 24959000, 2014).
tumor (continued). "Gelatinase activity was one major GO annotation of these eight genes (CA7, SPIB, GUCA2B, AQP8, IL6R, SPP1, TCN1, and CWH4) and is related to tumor progress and metastasis." (PMID 24959000, 2014). "Next, IHC assay was used to detect the expression of SPIB and STAT6 in tumor tissues." (PMID 39153969, 2024). "The results showed negative SPIB expression in normal breast and liver tissues, while tumor tissues showed moderate IHC staining." (PMID 35969172, 2022). "SCRIPro specifically enriches SPIB, a driver regulator that mediates apoptosis through the PI3K-AKT pathway in diffuse B-cell lymphoma, in tumor B-cells but not normal cells, while SCENIC+ fails to predict the SPIB activity in all the B-cells." (PMID 39024032, 2024).
cancer (16 papers, 2013 to 2024). A tumor composed of atypical neoplastic, often pleomorphic cells that invade other tissues. "To elucidate the association between SPIB expression and specific immune cell types in pan-cancer, we evaluated the correlation between SPIB expression and immune cell infiltration in pan-cancer based on the TIMER database." (PMID 35969172, 2022). "Forced expression or silencing of SPIB rescued the changes in proliferation and invasiveness of cancer cells caused by SPI1 knockdown or over‐expression." (PMID 34841706, 2021). "Therefore, examining genetic alterations associated with the SPIB gene in cancer patients is essential." (PMID 35969172, 2022). "In addition, SPIB was positively or negatively associated with prognosis in different cancers." (PMID 35969172, 2022). "The ANRS consists of five ANRGs: SPIB, CD24, NTRK3, EDA2R, and PLK1, all of which have been extensively linked to cancer." (PMID 39596658, 2024). "We also explored the role of SPIB in the immune response to further visualize its prognostic outlook in pan-cancer." (PMID 35969172, 2022). "Nonetheless, our pan-cancer study analysis of SPIB still provides the basis and novel insights for future studies." (PMID 35969172, 2022). "In a nutshell, our study demonstrates an important role for SPIB in cancer that is not limited to specific cancer types." (PMID 35969172, 2022). "In conclusion, we systematically and comprehensively investigated SPIB expression in pan-cancer to screen cancer types with poor prognosis and provide the foothold for future studies." (PMID 35969172, 2022). "In conclusion, these data suggest that SPIB expression determines the prognosis of patients with different types of cancers, in terms of OS, DSS, DFI or PFI." (PMID 35969172, 2022). "Although SPIB has been studied in more than 9 tumors, most studies have focused only on specific cancer types." (PMID 35969172, 2022). "Herein, we analyzed the differential expression of SPIB in pan-cancer using The Cancer Genome Atlas (TCGA) and Genotype-Tissue Expression (GTEx) databases and found that SPIB was significantly upregulated in most cancers." (PMID 35969172, 2022). "The results showed that SPIB expression affected DFI in patients with 3 cancer types, including COADREAD, OV, and READ." (PMID 35969172, 2022). "Collectively, SPIB enrichment with these gene sets implied its involvement in various cancer–related biological behaviors." (PMID 34094897, 2021). "However, further experimental validation of the therapeutic role of SPIB in these cancers is warranted." (PMID 35969172, 2022). "Mutation of these residues abolished the interaction between SPI1 and SPIB in cancer cells." (PMID 34841706, 2021). "SPIB facilitates SPI1 transactivation via physical interaction in cancer cells." (PMID 34841706, 2021). "There was increase and decrease in SPI1 enrichment, promoter‐luciferase reporter activity, as well as levels of HK2 and PGK1 in cancer cells stably over‐expressing or silencing SPIB, which was eliminated by silencing or ectopic expression of SPI1, respectively." (PMID 34841706, 2021). "Therefore, a deeper understanding of the relationship between SPIB and the immune microenvironment of different tumors is essential to provide the basis for exploring new immune-related therapeutic targets and clinical treatment of cancer." (PMID 35969172, 2022). "Therefore, the role of SPIB in different types of cancer remains to be further investigated." (PMID 35969172, 2022). "Thus a comprehensive pan-cancer study of SPIB may present a novel perspective on other tumors." (PMID 35969172, 2022). "Therapeutic targeting of SPIB/SPI1‐facilitated interplay of cancerous cells and neutrophils suppresses aerobic glycolysis and progression of cancer." (PMID 34841706, 2021). "Through physical interaction with SPI1‐related protein (SPIB), SPI1 drove expression of glycolytic genes within cancer cells, which in turn induced polarization of neutrophils via glycolytic metabolite lactate." (PMID 34841706, 2021).
cancer (continued). "We further explored cooperative roles of SPIB and SPI1 in aerobic glycolysis and cancer progression." (PMID 34841706, 2021). "Taken together, these data revealed that SPIB coordinated with SPI1 in driving glycolytic process and progression of cancer." (PMID 34841706, 2021). "Through physical interaction with its homologous partner SPIB, SPI1 is activated to promote aerobic glycolysis of cancer cells via upregulating HK2 or phosphoglycerate kinase 1 (PGK1), which in turn induces N2 polarization of neutrophils via glycolytic metabolite lactate." (PMID 34841706, 2021). "Thus, the roles of SPIB/SPI1 in aerobic glycolysis and cancer progression are warranted by further studies using syngeneic mouse models." (PMID 34841706, 2021). "Functional annotation of the three groups of SPIB target genes by DAVID tool shows that 'A' genes are enriched in the MAPK signaling pathway (145 genes), in cancer in general (173 genes), in the T cell receptor signaling (67 genes), and B cell receptor signaling pathways (49 genes)." (PMID 26099425, 2015). "In addition, upregulation of SPIB was observed in cancer cell lines, but not in non‐transformed and transformed normal cells, PNs or TANs." (PMID 34841706, 2021). "IGF1R, one of the members of the insulin/IGF system, was mostly expressed in foetal and cancer tissues 39 and three CpG islands are predicted in the promoter region of IGF1R which may combine large list of transcript factors including MZF1, TCFL5, USF1, ETS1 and SPIB." (PMID 33085184, 2020). "Validating co‐immunoprecipitation (co‐IP) assay indicated endogenous interaction of SPI1 with SPIB, but not with GATA2, in cultured cancer cells." (PMID 34841706, 2021).
infection (9 papers, 2012 to 2025). The state of being infected such as from the introduction of a foreign agent such as serum, vaccine, antigenic substance or organism. "The concentration of fecal lipocalin-2, a marker of intestinal inflammation, was significantly elevated in mice starting 3 d after infection with the S. Typhimurium wild type compared to mice infected with an avirulent S. Typhimurium invA spiB mutant." (PMID 40938708, 2025). "To investigate how virulence factors change the nutritional landscape of the gut, we compared cecal contents after mock infection or infection with either the virulent S. Typhimurium wild type (WT) or an avirulent invA spiB mutant." (PMID 39546570, 2024). "Due to the attenuation caused by mutations in invA and spiB, neither strain was recovered from the liver and spleen of mice seven days after infection." (PMID 23028318, 2012). "In contrast, SpiB+ club cells expressed increased levels of MHCII at day 10, and these levels were still increased at day 30 post-infection." (PMID 40750594, 2025). "When mice (CBA) were infected intragastrically with a 1:1 mixture of an invA spiB mutant (FF183) and a invA spiB pduA-X mutant (FF383), both strains were recovered in similar numbers from cecal and colon contents 14 days after infection." (PMID 28056091, 2017). "After an initial decrease, fecal pathogen burdens increased on days 3 and 4 after infection with the S. Typhimurium wild type, but not after infection with an avirulent invA spiB mutant." (PMID 40938708, 2025). "We investigated the impact of IAV infection on the number of SpiB-negative and positive epithelial cell populations at days 10 and 30 post-infection." (PMID 40750594, 2025). "In contrast, Sca1+ SpiB+ progenitors more than doubled at day 10 post-infection, while the numbers of SpiB-negative Sca1+ progenitors remained unchanged." (PMID 40750594, 2025). "Scoring of sections from the ileum collected 4 d after infection revealed inflammatory changes in mice infected with the S. Typhimurium WT, but not in mock-infected mice or mice infected with the invA spiB mutant." (PMID 39546570, 2024). "Ciliated cells were the most affected by the infection, with both SpiB-negative and positive populations more likely to express MHCII at day 10 and, while reduced, levels were still significantly increased at 30 post-infection compared to cells from naive mice." (PMID 40750594, 2025). "Thus, differences in cecal metabolite profiles triggered by infection with the virulent S. Typhimurium WT compared to infection with an avirulent invA spiB mutant were not due to differences in pathogen burden." (PMID 39546570, 2024). "SpiB-negative and positive Sca1+ progenitor cells expressed higher levels of MHC II at day 10 but not day 30 post-infection, compared to cells from naive mice." (PMID 40750594, 2025).